KCP (kielin cysteine rich BMP regulator)
Description:
Enhances bone morphogenetic protein (BMP) signaling in a paracrine manner. In contrast, it inhibits both the activin-A and TGFB1-mediated signaling pathways (By similarity).
Synonyms: CRIM2; KCP1; FLJ33365; NET67
Tractability: Antibody: UniProt places it where antibodies can reach, with medium confidence; UniProt predicts a signal peptide or a membrane-spanning region; its Gene Ontology location is reachable by antibodies, with medium confidence.
Gene: Protein-coding gene on chromosome 7 (128,862,042 to 128,910,719, reverse strand). Ensembl gene ENSG00000135253.
Subcellular location: Secreted
Gene Ontology:
Biological process: positive regulation of BMP signaling pathway
Cellular component: extracellular region; non-collagenous component of interstitial matrix
Genetic constraint (gnomAD): Loss-of-function variants: 188 observed, 188.83 expected, observed/expected ratio (o/e) 1, 90% interval 0.88 to 1.12. The upper end of that interval is the gene's LOEUF score, 1.12, which puts it in group 4 of 6, group 1 being the genes least tolerant of losing a copy. Missense variants: 1,988 observed, 1,946.3 expected, observed/expected ratio (o/e) 1.02, 90% interval 0.98 to 1.06. Synonymous variants: 804 observed, 773.56 expected, observed/expected ratio (o/e) 1.04, 90% interval 0.98 to 1.1.
Homologues: Orthologues: chimpanzee KCP (98% identical), macaque KCP (95% identical), pig KCP (84% identical), dog KCP (77% identical), mouse Kcp (77% identical), rat Kcp (76% identical), guinea pig KCP (74% identical), rabbit KCP (57% identical), tropical clawed frog kcp (51% identical), zebrafish kcp (45% identical). Paralogues in human: MUC5AC (22% identical), FCGBP (21% identical), MUC5B (21% identical), OTOG (19% identical), VWF (18% identical), OTOGL (17% identical), ZAN (16% identical), TECTA (16% identical), MUC19 (14% identical), MUC2 (14% identical), MUC6 (14% identical), CRIM1 (11% identical), and 7 more.
Diseases named in the same sentence as KCP in open-access papers:
KCP is named in the same sentence as 14 diseases in open-access papers, as found by Europe PMC text mining. Sharing a sentence is not in itself a finding about the gene and the disease. The quoted sentences say what the papers report.
acute myeloid leukemia (1 paper, 2025). Acute myeloid leukemia (AML) is a group of neoplasms arising from precursor cells committed to the myeloid cell-line differentiation. "CEBPA is a key factor of the acute myeloid leukemia signaling pathways, which may be significantly inhibited by KCP, as observed by the traditional IPA bioinformatics pathway analysis." (PMID 40297811, 2025).
cervical cancer (1 paper, 2025). A primary or metastatic malignant neoplasm involving the cervix. "KCP is associated with paclitaxel chemoresistance in cervical cancer." (PMID 40297811, 2025). "In future research, we will use various cell lines such as SiHa, Caski, HeLa, etc. to explore the mechanism of KCP’s involvement in paclitaxel resistance in cervical cancer." (PMID 40297811, 2025). "KCP increased resistance of cervical cancer to paclitaxel by enhancing cell proliferation and colony formation." (PMID 40297811, 2025). "Plasmids were constructed, lentiviruses were packaged, and human cervical cancer cell line (SiHa) cells were infected to obtain the KCP knockout SiHa strain." (PMID 40297811, 2025). "KCP is also significantly highly expressed in cervical cancer, especially in young Asian squamous cell carcinoma patients, and affects prognosis." (PMID 40297811, 2025). "Further testing confirmed the involvement of KCP in paclitaxel resistance of cervical cancer cells by examination of cell colony formation and proliferation." (PMID 40297811, 2025). "Considering the close relationship between KCP and paclitaxel resistance, KCP can be used as a candidate gene for paclitaxel resistance markers and therapeutic targets in cervical cancer in the future." (PMID 40297811, 2025). "The study showed that KCP knockout significantly inhibited colony formation and proliferation of cervical cancer cells in the paclitaxel group, thereby increasing the sensitivity to paclitaxel." (PMID 40297811, 2025). "This study is the first to explore the role of KCP in paclitaxel resistance in cervical cancer." (PMID 40297811, 2025). "We observed that KCP could act positively on the downstream gene SERPINB3 and negatively on the downstream gene CEBPA to affect the resistance of cervical carcinoma cells to paclitaxel." (PMID 40297811, 2025). "KCP can also act positively on the downstream gene SERPINB3 and negatively on the downstream gene CEBPA to participate in the proliferative function of cervical squamous carcinoma cells and affect the resistance of cervical carcinoma to paclitaxel." (PMID 40297811, 2025). "According to the IPA analysis of differentially expressed genes, qPCR was used to verify KCP could also act positively on the downstream gene of SERPINB3 and negatively on the downstream gene of CEBPA to affect the resistance of cervical carcinoma to paclitaxel." (PMID 40297811, 2025).
cervical squamous cell carcinoma (1 paper, 2025). A squamous cell carcinoma arising from the cervical epithelium. "In this study, we successfully generated a KCP knockout cervical squamous cell carcinoma in vitro model using CRISPR/Cas9 gene editing technology and preliminarily confirmed the regulatory function of KCP in SiHa cell line." (PMID 40297811, 2025). "SiHa is a human papilloma virus-related cervical squamous cell carcinoma line, resistant to cisplatin, we use this cell line to preliminarily explore the function of KCP in cervical squamous cell carcinoma." (PMID 40297811, 2025). "KCP knockout significantly reduced the resistance of cervical squamous cell carcinoma SiHa cells to paclitaxel." (PMID 40297811, 2025). "The effect of KCP knockout on cervical squamous cell carcinoma SiHa colony formation was assayed." (PMID 40297811, 2025).
diabetic kidney disease (1 paper, 2023). Progressive kidney disorder caused by vascular damage to the glomerular capillaries, in patients with diabetes mellitus. "Taken together, this study suggests that Sch B alleviates RTC EMT and mitochondrial dysfunction by KCP upregulation via Akt pathway inactivation and AMPK pathway activation in diabetic kidney disease." (PMID 38067580, 2023).
Hepatic steatosis (1 paper, 2017). Steatosis is a term used to denote lipid accumulation within hepatocytes. "In liver of aged mice or in mice fed with a high fat diet to induce NAFLD, loss of KCP promoted hepatic steatosis and fibrosis whereas expression of KCP transgene was protective." (PMID 29295498, 2017).
Hypertension (1 paper, 2022). The presence of chronic increased pressure in the systemic arterial system. "SNP rs4728142, an intergenic variant mapped to genes IRF5 and KCP, has been reported to be associated with hypertension in previous GWAS28." (PMID 36380121, 2022).
liver fibrosis (1 paper, 2017). "The remarkable effect of KCP on liver fibrosis deserve further analysis, it would be particularly interesting to analyse the contribution of BMP-modulation on KCP effects and how these data may translate into human disease." (PMID 29295498, 2017).
cancer (2 papers, 2025). A tumor composed of atypical neoplastic, often pleomorphic cells that invade other tissues. "As G12C is the most common KRAS oncogenic variant in LUAD, we used a recently developed KRASG12C-driven LUAD mouse model (named KcP) to test whether the additional loss of SETD2 (named KcP;Setd2) impacted cancer pathogenesis in vivo like it does in a G12D oncogenic mutant background." (PMID 40462961, 2025).
metabolic disease (1 paper, 2025). A congenital disorder (due to inherited enzyme abnormality) or acquired (due to failure of a metabolically important organ) disorder resulting from an abnormal metabolic process. "In 2002, Abreu’s research group discovered that Kielin/chondrin like protein (KCP) can affect the progression of certain chronic and metabolic diseases by regulating extracellular signals." (PMID 40297811, 2025). "In 2002, Abreu’s research group discovered that KCP could affect the progression of certain chronic and metabolic diseases via the regulation of extracellular signaling." (PMID 40297811, 2025).
tumor (1 paper, 2025). "We also studied the mechanism of action underlying the effect of KCP on tumor cell proliferation." (PMID 40297811, 2025). "This study suggests that KCP, which is an emerging protein, plays an important role in the proliferation of tumor cells, and its related mechanism has also been partially explored." (PMID 40297811, 2025). "Genes that inhibit tumor cell proliferation or that promote tumor cell apoptosis were selected, and KCP target genes were added and the gene relationship network diagram was drawn." (PMID 40297811, 2025).
KCP also shares sentences with these, for which no sentence is quoted: viral infection (2 papers); acute kidney injury (1); Obesity (1); respiratory infection (1).